MGMT (O-6-methylguanine-DNA methyltransferase)
Diseases named in the same sentence as MGMT in open-access papers (continued):
Sharing a sentence is not in itself a finding about the gene and the disease.
glioma (continued). "A common cognition has been reached that MGMT promoter methylation usually implied a better prognosis and increased TMZ sensitivity in glioma patients." (PMID 34462446, 2021). "Our study aims to explore the correlation between tumor grade, the status of IDH, MGMT, TERT and tumor perfusion indicators in glioma patients." (PMID 34814870, 2021). "This as well as the O6-methylguanine DNA methyltransferase (MGMT) methylation status are also a favorable prognostic factor in glioma." (PMID 34073442, 2021). "The DNA repair proteins MGMT and SP1 play important roles in TMZ resistance and are upregulated in TMZ-resistant glioma cell lines." (PMID 34316694, 2021). "With the completion of the Human Genome Project, some gene mutations have been shown to be aberrant in patients with gliomas and can be used for diagnosis and treatment of gliomas, such as IDH status, MGMT promoter status, and 1P/19q co-deletion etc." (PMID 33914773, 2021). "Our results showed that constructed multiparametric model from MRI radiomics features can identify IDH1, ATRX, MGMT, and EGFR in preoperative MRI scans of patients with glioma." (PMID 34056604, 2021). "Interestingly, the risk score of glioma patients in the CGGA cohort was elevated not only in the age >50 years, more malignant type of 2016 WHO classification, higher grade, IDH wild type, and MGMT promoter unmethylated subgroups, but also in the male and 1p19q non-codel patients." (PMID 34095147, 2021). "Important prognostic glioma biomarkers include isocitrate dehydrogenase (IDH), chromosome arms 1p/19q-codeletion, methylguanine-DNA methyltransferase status (MGMT)." (PMID 34676470, 2021). "Among patients with WHOIII gliomas, it was shown that the expression level of SYP was higher in patients with MGMT promoter methylation." (PMID 34136394, 2021). "At the same time, we verified the expression levels and status of well-known molecular markers including MGMT promoter methylation, IDH1 mutant, and co-deletion of 1p19q in low-grade glioma patients (WHOII, WHOIII) between high and low expression of SYP." (PMID 34136394, 2021). "Age, extent of resection, number of gliomas, MGMT methylation status and preoperative SIRI levels were important factors related to the prognosis of high grade gliomas, so they were included in the nomogram." (PMID 34055639, 2021). "The correlation of MGMT, BCRP1, and A2B5 expression with prognosis of glioma patients was investigated through Kaplan–Meier survival curve analysis with a log-rank test of 50 GBM patients." (PMID 33562724, 2021). "The results showed that there was a positive correlation between NUP37 and most known biomarkers of glioma such as ATRX, EGFR MGMT, CDK4, and so on." (PMID 34264013, 2021). "Increased CAFs infiltration in gliomas is significantly correlated with older age, high tumor grade, IDH status, 1p/19q status and MGMT promoter status, tumor purity, immune score, stromal score, ESTIMATE score, stemness score, and patient prognosis." (PMID 34778248, 2021). "In 2016, the revised classification of central nervous system tumors was constructed based on genetic and epigenetic alterations, including IDH 1/2, MGMT methylation, 1p/19q codeletion, and EGFR." (PMID 34568031, 2021). "In this context, SP-141 was able to sensitize gliomas to TMZ, and this occurred independently of the MGMT status." (PMID 32630235, 2020). "Qiu and colleagues demonstrated that elevated O6-methylguanine DNA methyltransferase (MGMT) expression and activity in glioma stem-like cells were responsible for temozolomide resistance." (PMID 32823711, 2020). "For example, Temozolomide, a DNA alkylating agent, is very effective for the treatment of primary glioma, but suffers from MDR due to the DNA repair function of O6-methylguanine methyltransferase (MGMT)." (PMID 32029822, 2020).
glioma (continued). "Studies predicting glioma genes based on radiomics mainly focused on the IDH, 1p/19q, MGMT, ATRX, and EGFR genes, which all agreed that radiomics was an excellent noninvasive method for predicting the genetic status of glioma." (PMID 32509858, 2020). "Overall survival of all glioma, AA and GBM cases based on MGMT methylation: median overall survival based on MGMT methylation was derived from cases with available MGMT methylation status data, which was 23 cases." (PMID 33282092, 2020). "The results revealed that the risk score has a significant correlation with the clinical features of glioma, including TCGA transcriptome subtypes, WHO grade, IDH1 status, 1p/19q status, and MGMT promoter methylation status." (PMID 33230136, 2020). "There appears to be survival benefit for patients with MGMT promoter methylation in both grade III and IV patients, and 1p19q co-deletion in grade III glioma." (PMID 32005184, 2020). "In the current study, we found a significant correlation between MGMT promoter methylation and IDH1 status in glioma cases (p = 0.03)." (PMID 33552543, 2020). "The results revealed that the expression of MGMT and MPG in most patient-derived gliomas cells was lower than detected in control (T98G) cells." (PMID 33335215, 2020). "Other studies on larger cohorts have previously been conducted, such as The Cancer Genome Atlas (TCGA) or the Chinese Glioma Genome Atlas (CGGA), and the methylation of MGMT promoter and the copy number status were part of the data they gathered." (PMID 32666673, 2020). "By analyzing a large cohort of IDH-wildtype and mutant recurrent gliomas treated with TMZ, we have discovered that a subset of patients carries distinct MGMT genomic rearrangements." (PMID 32753598, 2020). "MGMT appeared to carry greater prognostic value in our patients for grade III and IV glioma patients." (PMID 32005184, 2020). "Therefore, our study investigated whether histogram profiling of ADC distinguishes grade I from grade II glioma, reflects the proliferation index Ki-67, as well as the IDH (isocitrate dehydrogenase) mutation and MGMT (methylguanine-DNA methyl-transferase) promotor methylation status." (PMID 32158691, 2020). "Recently, reports had been published that several biomarkers such as MGMT, STAT3, and APNG were involved in the TMZ resistance of gliomas." (PMID 33362537, 2020). "It has been shown that inhibition of NF-κB results in anti-glioma activity, and also reduces TMZ-induced chemoresistance via down-regulation of O6-methylguanine-DNA methyltransferase (MGMT) gene expression." (PMID 35582224, 2020). "Here, standard-of-care therapy was predominantly recommended for newly diagnosed IDH-wild-type and IDH-mutant glioma, with the option of considering shorter courses of radiotherapy and avoidance of temozolomide in IDH-wild-type MGMT unmethylated tumors." (PMID 32493443, 2020). "Very recently, another MGMT gene fusion, ASAP2-MGMT, with similar features to the fusions that we have described here in gliomas, has been identified in a medulloblastoma patient that relapsed after TMZ treatment." (PMID 32753598, 2020). "XIST/miR-29c correlation has been revealed to regulate DNA repair protein MGMT and transcription factor specificity protein 1 (SP1), participating in conferring TMZ resistance of gliomas." (PMID 32977537, 2020). "Nonetheless, we show that in patients with suspected glioma (HGG and LGG); mean APTw signal is more elevated in MGMT methylated patients 2.38% (n = 10) vs. 1.92% (n = 3)." (PMID 33373375, 2020). "In our own cohort, 9/100 gliomas were hypermutated, all 9 had been previously treated with TMZ, all 9 had MGMT promoter methylation, and 5/9 were IDH1 mutant." (PMID 32051040, 2020). "Forty‐six glioma samples and one non‐neoplastic brain sample were analyzed by MS‐HRM in terms of SFRP1, SFRP2, RUNX3, CBLN4, INA, MGMT, and RASSF1A promoter methylation." (PMID 32783304, 2020).
glioma (continued). "Glioma cells secrete EVs containing proteins (EGFR/EGFRvIII, MGMT and APNG) and RNAs (miR-21, miR-23, miR-29a, miR-30a, miR-221 and miR-451) to regulate the proliferation of recipient cells via several signaling pathways (AMPK, AKT, and MAPK) 54-57." (PMID 32550897, 2020). "Our prognostic cut-off points appear consistent with what has been reported in glioma WHO grade III and IV; although comparison is hampered across various institutions as different methods on determining MGMT promotor status are being used." (PMID 33184319, 2020). "We further observed that five lncRNAs interact and are closely related to the clinical symptoms of glioma patients (WHO grade, IDH1 status, 1q19q status, and MGMT)." (PMID 33391355, 2020). "Regarding the MGMT promoter status in the CGGA database, we found that gliomas with a methylated MGMT promoter had lower GLRX expression compared to those in the unmethylated group." (PMID 33329553, 2020). "In our previous study, we have analyzed the profile of aberrant methylation of MGMT, RASSF1A, p15INK4B, and p14ARF genes in serum free-circulating DNA and corresponding tumor tissue in a group of CNS cancer patients." (PMID 32493231, 2020). "We evaluated the clinical impact of MGMT autoantibody status and the level of the prediction of recurrence‐free survival (RFS) in 56 glioma patients with various grade (WHO grade II, n = 16; WHO grade III, n = 25; WHO grade IV, n = 15)." (PMID 31210005, 2019). "Aberrant methylations of MGMT, TERT, and EGFR have been reported to have potential value in diagnosing gliomas." (PMID 31708732, 2019). "In this study, we investigated the relationship between SWI features and glioma grades, and the expression of key molecular markers isocitrate dehydrogenase 1 (IDH1), O-6-methylguanine-DNA methyltransferase (MGMT), and 1p19q." (PMID 31745161, 2019). "Previous studies on glioma have revealed many molecular markers, such as IDH, 1p19q, MGMT, sarcomarcoma proto oncogene B, telomerase reverse transcriptase tert, and epidermal growth factor receptor." (PMID 30995921, 2019). "We analyzed the role of the glioma ITSS grade in predicting pathological grade and the expression status of IDH1, MGMT, and 1p19q." (PMID 31745161, 2019). "A total of 201 serum samples of glioma patients with various WHO grade and 311 serum samples of healthy donors were examined for the detection of MGMT autoantibodies by peptides microarray." (PMID 31210005, 2019). "The methylation status of the O6-methylguanine-DNA methyltransferase (MGMT) promoter has emerged as a favorable independent prognostic and predictive biomarker in glioma." (PMID 31426864, 2019). "Surgical resection, radiotherapy, and TMZ chemotherapy are the standard therapy for glioma patients, but seriously, side effects and the resistance to TMZ due to the expression of MGMT resulted in limiting efficacy of this treatment." (PMID 31814867, 2019). "The effect of chronic TMZ on the MAPK signaling pathway, and on the expression of MGMT, a crucial target for TMZ in glioma cells, was explored." (PMID 30131700, 2018). "We have demonstrated that PAM-OBG is able to generate O6BG inside glioma, via MAOB, and that this O6BG then reacts with MGMT inactivating it." (PMID 29844863, 2018). "This pattern is in accordance with other studies where MGMT promoter is reported methylated in 30–60% of GBM31 and in 30–90% of low-grade gliomas including Astrocytoma and Oligidendrioglioma13,17,21." (PMID 29712977, 2018). "The current study investigated the concordance between MGMT gene methylation status and its protein expression to determine their correlation with TMZ therapy in a series of glioma patients of varied histologies." (PMID 29712977, 2018).
glioma (continued). "In cultured glioma cells, we show that PAM-OBG is converted to O6BG, inhibiting MGMT and sensitizing cells to DNA alkylating agents such as BCNU, CCNU, and Temozolomide (TMZ)." (PMID 29844863, 2018). "Cells and xenografts derived from newly diagnosed MGMT methylated high-grade gliomas were sensitive to TMZ while those derived from unmethylated and recurrent gliomas were typically resistant." (PMID 30153289, 2018). "In this study, protein expression revealed that higher levels of MGMT and Cx43 correlated with TMZ-resistance in glioma cells." (PMID 29301329, 2018). "In the present study, we monitored the protein levels of MSH6, MGMT, and SP1 in response to cotransfecting XIST and miR-29c in TMZ-resistant glioma cell lines." (PMID 28831025, 2017). "Serum cell-free DNA methylation levels of Alu, MGMT, P16, RASSF1A from 124 glioma patients and 58 healthy controls were detected by the bisulfite sequencing." (PMID 29100349, 2017). "We detected four genes (Alu, MGMT, RASSF1A, P16) in the serum of 124 glioma patients and 58 healthy controls." (PMID 29100349, 2017). "The inhibition of microRNA‐29c suppressed MGMT expression and led to increased TMZ efficacy in both culture glioma cells and xenograft models." (PMID 28297578, 2017). "In the present study, we use the bisulfite sequencing (BSP), to detect the methylation status of Alu, MGMT, RASSF1A, and P16 in serum cell-free DNA of glioma patients compared to healthy controls." (PMID 29100349, 2017). "Our data suggest that XIST can amplify the chemoresistance of glioma cell lines to TMZ through directly targetting miR-29c via SP1 and MGMT." (PMID 28831025, 2017). "We reported the clinical impact of both promoter methylation and genotypes in MGMT, a negative regulator of TMZ treatment, to glioma patients." (PMID 28575062, 2017). "Combination treatment with WA and TMZ resulted in resensitization of MGMT mediated TMZ-resistance by Akt/mTOR pathway inhibitory modulation, which probably enhance the autophagic cell death in PTEN-null U87 glioma cells." (PMID 26830677, 2016). "We must also point it that a surprising proportion of IDH mutant gliomas are unmethylated—this may reflect the relative insensitivity of MS-PCR (methylation-specific polymerase chain reaction) compared to other methods, for example DNA pyrosequencing, for MGMT promoter methylation." (PMID 27834917, 2016). "In the OP group with advanced gliomas, age ≤ 70 (P = 0.018), higher KPS score (KPS ≥ 80, P < 0.001) and MGMT promoter methylation (P = 0.015) were significantly associated with OS in multivariate Cox analysis." (PMID 27590514, 2016). "GANT61 sensitizes glioma cells to TMZ treatment by enhancing DNA damage effect, decreasing MGMT expression and the Notch1 pathway." (PMID 27894350, 2016). "We investigated levels of multiple drug resistance-related genes in U87 and primary glioma cells, including genes related to drug efflux (ABCB1, ABCC1, ABCC2, ABCC4, ABCG2, ATM), DNA damage repair (MGMT) and stemness (CD133)." (PMID 27486877, 2016). "The promoter methylation of O-6-methylguanine-DNA methyltransferase (MGMT) and IDH-1 have been designated as meaningful molecular biomarkers for glioma in the National Comprehensive Cancer Network (NCCN) guidelines." (PMID 27763568, 2016). "Thus silencing the expression of MGMT gene is a relevant advantage for patients affected by glioma upon treatment with temozolomide, and a thorough understanding of the mechanisms of regulation of MGMT gene expression could provide useful hints for innovative therapeutic approaches." (PMID 27057640, 2016). "Several studies have shown a high rate of MGMT promoter methylation in grade II and III gliomas, which subsequently was demonstrated to be related to IDH mutational status and G-CIMP." (PMID 25943885, 2015). "The O6-methylguanine-DNA methyltransferase (MGMT) upregulation in GBM makes it resistant to Temozolomide (TMZ), a well-known drug for glioma." (PMID 25866775, 2015).
glioma (continued). "In summary, in the largest randomised trial in chemonaïve patients with recurrent high grade glioma we were able to demonstrate the independent prognostic significance of IDH1/2 and MGMT methylation status, and potentially PTEN status, for survival." (PMID 24952577, 2014). "Increased activity of the MGMT gene inhibits the effects of TMZ, the standard alkylating chemotherapeutic agent used to treat gliomas and explains why some patients fail to benefit from this treatment." (PMID 25147764, 2014). "The expression of the DNA repair protein, O6-Methylguanine-DNA Methyltransferase (MGMT), was inversely related to invasion capacity of glioma and to α5β1 integrin expression." (PMID 24216697, 2013). "Additionally, hypermethylation of O6-methylguanine DNA methyltransferase (MGMT), a DNA repair protein that prevents G:C > A:T point mutations by removing alkyl adducts from the O6 position of guanine, may lead to IDH1 and RAS mutations in gliomas." (PMID 23414134, 2013). "Furthermore, TMZ-induced early phosphorylation of Chk1 was noted in glioma cells regardless of whether they were MGMT-proficient or MGMT-deficient, and regardless of their MMR status." (PMID 23667469, 2013). "Using MGMT-siRNAs and a novel liposome, LipoTrustTM EX Oligo for delivery, MGMT was efficiently knocked down in glioma cells lines, GBM-stem like cells, and in vivo glioma tumors." (PMID 24287492, 2013). "Many studies have demonstrated that DNA repair pathways, such as MGMT, BER and MMR, reverse chemotherapy-induced damage and mediate resistance in gliomas." (PMID 24287492, 2013). "Beside MGMT, the drug efflux transporters ABCB1 and ABCG2 are thought to affect survival of glioma patients due to their role in drug resistance." (PMID 24380367, 2013). "MGMT expression inversely correlates with sensitivity to the alkylating agents TMZ and carmustine in glioma cells and glioma stem-like cells." (PMID 24287492, 2013). "The relationship between SATB1 expression, clinicopathological parameters, Ki67 expression and MGMT promoter methylation status was evaluated, and the prognostic value of SATB1 expression in patients with gliomas was analyzed." (PMID 22839214, 2012). "The same question applies to low-grade glioma where radiation versus temozolomide treatment is tested (EORTC 22033-26033, NCT00182819) and the role of CIMP and MGMT methylation will need to be dissected." (PMID 22810491, 2012). "This is in contrast to grade II and III glioma (VB-Glioma-III and T-GliomaII/III) in which MGMT is methylated in basically all CIMP tumors according to our classification model." (PMID 22810491, 2012). "Among gliomas, in particular LGGs, LINE-1 methylation levels were significantly proportional to MGMT promoter methylation." (PMID 21829728, 2011). "We found that the MGMT promoter methylation level was directly proportional to LINE–1 methylation in a statistically significant manner (r = 0.335, p<0.001) for all glioma samples and normal brain tissue." (PMID 21829728, 2011). "The probable positive response for temozolomide may be due to the low level of the DNA repair enzyme O6-methylguanine-DNA methyltransferase (MGMT), demonstrated by our negative immunostaining, as absence of this enzyme in gliomas is associated with increased chemosensitivity." (PMID 22011735, 2011). "The promoters of the RASSF1A (3p21.3), BLU (3p21.3) and MGMT (10q26) genes were analyzed by MCA-MSP and MCA-Meth in 13 astrocytoma samples, 6 high grade glioma cell lines and 4 neuroblastoma cell lines." (PMID 18298842, 2008). "Here we established glioma models from NHA cells and demonstrated that MGMT is downregulated in the transformed astrocyte cells." (PMID 17547775, 2007).